TM4SF20 (transmembrane 4 L six family member 20)
Description:
Polytopic transmembrane protein that inhibits regulated intramembrane proteolysis (RIP) of CREB3L1, inhibiting its activation and the induction of collagen synthesis. In response to ceramide, which alters TM4SF20 membrane topology, stimulates RIP activation of CREB3L1. Ceramide reverses the direction through which transmembrane helices are translocated into the endoplasmic reticulum membrane during translation of TM4SF20, this mechanism is called 'regulated alternative translocation' (RAT) and regulates the function of the transmembrane protein.
Synonyms: FLJ22800; TCCE518; PRO994; SLI5
Tractability: Antibody: its Gene Ontology location is reachable by antibodies, with high confidence; UniProt predicts a signal peptide or a membrane-spanning region; the Human Protein Atlas places it where antibodies can reach.
Gene: Protein-coding gene on chromosome 2 (227,362,038 to 227,381,995, reverse strand). Ensembl gene ENSG00000168955.
Subcellular location: Membrane; Endoplasmic reticulum membrane
Subcellular location (Human Protein Atlas): Focal adhesion sites; Plasma membrane
Gene Ontology:
Molecular function: protein binding
Biological process: negative regulation of proteolysis
Cellular component: endoplasmic reticulum membrane; plasma membrane; membrane
Genetic constraint (gnomAD): Loss-of-function variants: 15 observed, 18.81 expected, observed/expected ratio (o/e) 0.8, 90% interval 0.53 to 1.23. The upper end of that interval is the gene's LOEUF score, 1.23, which puts it in group 5 of 6, group 1 being the genes least tolerant of losing a copy. Missense variants: 282 observed, 283.48 expected, observed/expected ratio (o/e) 0.99, 90% interval 0.9 to 1.1. Synonymous variants: 92 observed, 100.95 expected, observed/expected ratio (o/e) 0.91, 90% interval 0.77 to 1.08.
Homologues: Orthologues: chimpanzee TM4SF20 (99% identical), macaque TM4SF20 (91% identical), mouse Tm4sf20 (75% identical), rabbit TM4SF20 (75% identical), dog TM4SF20 (74% identical), rat Tm4sf20 (74% identical), pig TM4SF20 (73% identical), guinea pig TM4SF20 (69% identical), tropical clawed frog tm4sf20 (41% identical). Paralogues in human: TM4SF1 (26% identical), TM4SF5 (26% identical), TM4SF4 (25% identical), TM4SF19 (21% identical), TM4SF18 (19% identical).
Diseases named in the same sentence as TM4SF20 in open-access papers:
TM4SF20 is named in the same sentence as 3 diseases in open-access papers, as found by Europe PMC text mining. Sharing a sentence is not in itself a finding about the gene and the disease. The quoted sentences say what the papers report.
language delay (2 papers, 2024 to 2025). "The TM4SF20 is associated with early language delay and white matter hyperintensities (WMH) phenotypes reported in a study of 15 probands with language delay phenotype." (PMID 39334596, 2024).
cancer (2 papers, 2014 to 2023). A tumor composed of atypical neoplastic, often pleomorphic cells that invade other tissues. "Tetraspanins, of which mRNA for TM4SF4, TM4SF20 and PLLP were increased >10-fold in SSA/Ps, regulate cell adhesion and proliferation by binding integrins and growth factor receptors, are increased in multiple types of cancer and regulate epithelial-to-mesenchymal transition." (PMID 24533081, 2014).
tumor (2 papers, 2022 to 2024). "In addition, TM4SF20 promoter methylation in tumors was closely associated with tumor stage: stage I tumors in LIHC patients were markedly more likely to have lower methylation levels." (PMID 38206300, 2024).